ICAM1 (intercellular adhesion molecule 1)
Diseases named in the same sentence as ICAM1 in open-access papers (continued):
Sharing a sentence is not in itself a finding about the gene and the disease.
infection (continued). "Parasite load (left) and percentage of parasite sequestration (right) in the brain of mice at day 6 post-infection upon treatment with α-ICAM1 antibody or its isotype control, quantified by intravital microscopy (N=3 in 3 independent infections)." (PMID 35787830, 2022). "The interactions of lymphocyte LFA-1 with ICAM-1 expressed by these DCs, elevated upon infection, maturation and entry into MedLNs, were thought to be critical for functional immune synapses between both CD4+ and CD8+ T cells and antigen presenting DCs." (PMID 36895258, 2022). "The results from pre-clinical models have indicated a strong potential for ICAM-1 blockage of HRV infections." (PMID 35316427, 2022). "Collectively, the evidence strongly indicate the substantial diversity of HRVs and their ability to utilize host receptors such as ICAM-1 for invasion and infection." (PMID 35316427, 2022). "LFA-1 mainly functions to mediate the migration of immune cells to the site of infection as it adheres to the intercellular adhesion molecule 1 (ICAM-1) expressed on vascular endothelial cells." (PMID 35051027, 2022). "The synthesized γ3-RBCNPs achieve targeted therapy using the specific binding ability of γ3 peptide to ICAM-1 at the infection site." (PMID 35783411, 2022). "Next, we detected the ICAM-1 mRNA expression level in four tissues after F. columnare invasion, which showed moderately upregulated expression after infection in the mass." (PMID 34489953, 2021). "ICAM-1 is cell adhesion molecule and play an important role in the migration of leukocytes or monocytes to the infection site." (PMID 34436268, 2021). "We also observed that lasR mutant infections elicit greater ICAM-1 expression in the bronchial epithelium and greater lung inflammation in murine infections, but this association remains to be mechanistically proven in vivo." (PMID 33690714, 2021). "CVA21 is capable of infecting normal cells that express ICAM-1, however, these cells can prevent the spread of infection through innate antiviral defenses." (PMID 34503272, 2021). "The parasite has been shown to use ICAM-1 to cross the blood-brain barrier and other endothelial barriers during the acute phase of infection." (PMID 33602170, 2021). "The expression of IL-1β, IL-6, IL-8, IL-18, TNF-α, MMP-9, RANKL, TLR-2, TLR-4, TLR-6, thymic stromal lymphopoietin (TSLP), and ICAM-1 was evaluated by qPCR at 2 and 24 h after infection." (PMID 33802988, 2021). "The level of ICAM-1 expression is upregulated in response to some inflammatory stimulations, including pathogen infection and proinflammatory cytokines." (PMID 34489953, 2021). "In an experiment with HRV14, another HRV strain used ICAM-1 as receptor for entrance of epithelial cells, IL-6 and IL-8 levels were found to increase by the infection." (PMID 34001091, 2021). "For example, C8161 and SK-MEL-103 cells have low levels of ICAM-1 expression yet exhibit high levels of viral RNA following infection." (PMID 34503272, 2021). "The RV14 infection stimulated the cytokine production and also of messenger RNA (mRNA) of ICAM-1 in epithelial cells." (PMID 33937285, 2021). "Although no significant expression of ICAM-1 in the gills was detected after challenge at all time points, mildly increased expression of ICAM-1 gene was detected at 28 d post infection." (PMID 34489953, 2021). "The infection of BALB/c mice with L. donovani parasite resulted in increased intercellular adhesion molecule 1 (ICAM-1) and B7-1 (CD80) expression by infected macrophages." (PMID 33680991, 2021). "Endothelial cells do however sense and respond to infection in the adjacent epithelial cells, increasing ICAM‐1 expression and releasing pro‐inflammatory cytokines." (PMID 34721846, 2021). "Our results showed that BAE cell infection by E. ruminantium resulted in the over-expression of several ECs surface proteins, such as ICAM1, VCAM1, CSF1, ESM1 and MCAM." (PMID 34073568, 2021).
infection (continued). "Results of antibody staining on adherent HMECs showed that ICAM-1 and E-selectin were slightly upregulated on HMECs after OT infection." (PMID 34368012, 2021). "For example, NO level is associated with vasoconstriction, pro-inflammatory and cell-mediated immunity (CMI) cytokines, HMGB1, IL-33, neopterin, ICAM1, and complement components are most related to inflammation and infection." (PMID 34679434, 2021). "When compared to the gills and skin, the expression level of ICAM-1 was lower increased after infection." (PMID 34489953, 2021). "As to the expression of ICAM-1, Toxoplasma gondii results in increased ICAM-1 expression in the jejunum of rats after infection, and ICAM-1 expression increased in the skin of mice after vaccination with Schistosoma mansoni." (PMID 34489953, 2021). "The data indicate a link between the activation of the three major MAPK pathways, NF-κB, and the upregulation of ICAM-1 gene expression induced by adenoviral vectors in the initial phase of infection." (PMID 34639132, 2021). "Instead, we found that infection with P. gingivalis induced clustering of ICAM-1 in HD-MVEC and that the majority of internalized bacteria co-localized with ICAM-1 positive vesicles." (PMID 32341760, 2020). "Blocking CD11b or ICAM1 using antibodies inhibits Ly6Chi monocyte recruitment to the liver during infection with Listeria monocytogenes." (PMID 32101593, 2020). "Ultimately, the upregulation of effector molecules, such as cytokine TNF, cytolytic molecule perforin (PRF1), and adhesion molecule ICAM1, enhance the protection against infection, killing of bacterial-infected cells, and cell migration to infected tissues." (PMID 32582206, 2020). "The presence of platelets during the infection of both types of endothelial cells induced a significant upregulation of ICAM-1 expression compared to infected cells or cells incubated with platelets alone (p < 0.0005)." (PMID 32867217, 2020). "In contrast, U266-84 cells did not express CD86 and displayed the greatest reductions in CD70 and ICAM-1 upon LOAd infection." (PMID 32355275, 2020). "The endothelium in infected lungs presented progressive Tie2 malfunction, increased Ang2 and ICAM-1 expression and pro-inflammatory MΦs at the onset of disease and severe stages of infection." (PMID 32119672, 2020). "Since ICAM-1 is a specific ligand for β2 integrins, these combined data indicate that infection of mDCs with HSV-2 fosters β2 integrin-dependent adhesion." (PMID 31963276, 2020). "On the other hand, the presence of platelets during the infection of HBMECs induced a significant (p < 0.0005) upregulation of ICAM-1." (PMID 32867217, 2020). "These current findings largely support the notion that both PDGF-BB and ICAM-1 are two critical host targets that can be induced by meningitic E. coli for successful infection of the CNS." (PMID 31092253, 2019). "In hBMEC model, we found that mRNA transcription as well as the protein level of ICAM-1 showed a significant and time-dependent increase accompanying the infection." (PMID 31092253, 2019). "Meanwhile at the protein level, we also observed a significant increase of ICAM-1 in brains of the infected mice and maintained the higher expression in the course of infection." (PMID 31092253, 2019). "In vivo, by using MSD Multi-Array® assay, we evaluated the contribution of ICAM-1 to the production of proinflammatory cytokines in response to the infection, by intravenous injection of the ICAM-1 neutralizing antibody prior to bacterial challenge." (PMID 31092253, 2019). "Our data show significant elevation (p ≤ 0.001) of ICAM-1 following infection with CVB3 in wildtype animals." (PMID 31337812, 2019). "MCP‐1 and ICAM‐1 are involved in the adhesion and migration of leukocytes and recruit leukocytes to sites of inflammation produced by tissue injury or infection." (PMID 31062470, 2019).
infection (continued). "In contrast, high levels of Icam1 were detected in Myd88−/− mice infected with H. felis for 25 weeks that were reduced but still high at 47 weeks post-infection." (PMID 31065023, 2019). "Expression of ICAM-1 in human IECs is upregulated following infection with invasive bacteria and stimulation with TNF-α and IFN-γ." (PMID 31035617, 2019). "Upregulation of ICAM-1 on the other hand was shown to initiate the inflammatory response of the CNS, mediating neutrophils or monocyte recruitment during infection." (PMID 31671896, 2019). "Intercellular adhesion molecule-1 (ICAM-1) was also observed to be aiding infection of mouse cells by coxsackievirus A21 and rhinovirus thereby acting as its receptor." (PMID 31215493, 2019). "Cell adhesion molecules such as Vcam1 and Icam1 play a role in leukocyte migration to the site of infection." (PMID 31166414, 2019). "ICAM-1 is responsible for the transmigration of leukocytes during an infection, which occurs through the endothelium to the site of the lesions." (PMID 31921058, 2019). "In summary, our study revealed that the MIF induced by P. gingivalis ATCC 33277 infection not only promoted ICAM-1 expression inendothelial cells but also activated monocyte-endothelial cell adhesion." (PMID 29482504, 2018). "The present study showed that the infection with PbA increased ICAM-1 and VCAM-1 mRNA expression in the brain of infected mice." (PMID 29367729, 2018). "ICAM1 is expressed at only low levels by unstimulated ECs, but exposure to proinflammatory cytokines or infection can upregulate its expression." (PMID 30401896, 2018). "Resistin also upregulates intercellular adhesion molecule-1 and chemokine (C-C motif) ligand 2, which participate in leukocytes’ recruitment pathways at infection sites." (PMID 29584687, 2018). "Patients who developed VAP also showed a trend to increased levels of the pro-inflammatory mediators IL-6, IL-8 and ICAM-1, reflecting an inflammatory response to infection." (PMID 30283005, 2018). "This was brought about by repeated blind infection cycles alternating between ICAM-1-deficient Cos-7 cells and boosting in (ICAM-1-expressing) HeLa cells." (PMID 28368306, 2017). "Prior to lysis, HSV-1 infected iDCs downregulate surface expression of adhesion as well as costimulatory molecules, including CD1a, CD40, ICAM-1 (CD54) and later during infection CD80 and CD86." (PMID 29163433, 2017). "Our studies revealed the dynamic changes in these adhesion molecules, and the expression level of ICAM-1 was the highest, with a peak at day 3 post-infection by QRT-PCR and day 5 post-infection by Western Blot." (PMID 28824565, 2017). "The reduction in parasite tissue sequestration in infections of ICAM-1 null mice is maintained after mosquito transmission." (PMID 28468674, 2017). "The expression of ICAM-1 was much higher than that of the other genes during the first 5 days post-infection (p < 0.0001)." (PMID 28824565, 2017). "ICAM-1 facilitates recruitment of circulating leukocyte (including lymphocytes) to infection/inflamed sites and mediates the interaction between T cells and their target cells." (PMID 28143561, 2017). "Since the expression of ICAM-1 plays key role in the recruitment and extravasation of circulating leukocytes at sites of infection, it induces subsequent activation of inflammation." (PMID 27543097, 2016). "Prior to infection, ICAM‐1 mRNA expression and the concentrations of sICAM‐1 were significantly lower in the cells that were pretreated with L‐carbocisteine than in the cells that were pretreated with vehicle in both groups of subjects." (PMID 27957326, 2016). "There is a report that macrophages from Balb/c mice upon infection with L. donovani show decrease in B7.1 expression whereas ICAM1 expression is increased." (PMID 27214205, 2016).
infection (continued). "No significant change in the localization of follicular dendritic cells (FDC-M1+; red) in GCs (PNA+; green) or in the percentage of this cell population (FDC-M2+, ICAM-1+) was seen following infection with either of these viruses." (PMID 27892498, 2016). "Macrolide antibiotics such as erythromycin inhibit infection by the major group of HRVs via a reduction in ICAM-1 expression." (PMID 25860871, 2015). "Macrophages from infected BAL of WT and Rip3-/- mice had significant upregulation of CD54 (ICAM-1), a major activation marker of macrophages, consistent with an immunostimulatory phenotype evoked by infection, shown in absolute numbers and as a percentage." (PMID 25880560, 2015). "HRV-2 or HRV-4 infection increased ICAM-1 mRNA expression, but these increases were reduced by the addition of PA and PGG." (PMID 25860871, 2015). "In contrast, another study produced contradictory results to ours, with higher levels of IL-8, IL-6, and ICAM-1 expression in CTRL cells (CFT1-LCFSN) compared to CF cells (CFT1-ΔF508) after infection." (PMID 26485688, 2015). "In contrast, pretreatment and treatment with EM900 before and after RV14 infection reduced ICAM-1 mRNA expression after infection." (PMID 26462747, 2015). "It utilizes membrane‐bound ICAM‐1 as host receptor for infection, while sICAM‐1 is known to neutralize rhinovirus." (PMID 24994897, 2014). "Similar to mRNA expression, western blotting further demonstrated the increase in the protein expression of both E-selectin and ICAM-1 in the brains of WT mice at day 8 after infection." (PMID 24750819, 2014). "As anticipated, a 10- to 25-fold increase in the mRNA expression of ICAM-1 and E-selectin were observed in the brains of WT mice compared to corresponding mock-infected mice at day 8 after infection." (PMID 24750819, 2014). "Our data show that infection of PHH with H. hepaticus leads to the up-regulation of ICAM-1 as shown by Real-Time PCR, 2-PM and FACS." (PMID 24932686, 2014). "Similar to previous reports, KSHV rapidly induced phosphorylation of NF-κB p65 and IkBα within 20 minutes of infection, an effect that correlated with changes in expression of the NF-κB-controlled intracellular adhesion molecule 1 (ICAM-1)." (PMID 24701351, 2014). "Infection with WNV (NY99 strain) significantly induced ICAM-1, VCAM-1, and E-selectin in human endothelial cells and infected mice brain, although the levels of their ligands on leukocytes (VLA-4, LFA-1and MAC-1) did not alter." (PMID 25036379, 2014). "Together, an ICAM-1-based RABV vaccine holds the potential to influence B cells responses directly by aiding in B cell infection, B cell activation and B:T interactions, resulting in enhanced anti-RABV antibody responses." (PMID 24489846, 2014). "Such an increase in ICAM-1 would be expected to make the cells more vulnerable to RV16 infection, with increased binding and entry of virus into the cells leading to enhanced viral replication." (PMID 24705919, 2014). "Together, these data indicate that expression of ICAM-1 from a rRABV-based vaccine enhances infection of primary murine splenocytes, with a propensity for infecting B cells." (PMID 24489846, 2014). "We found that while ICAM-1 expression peaked at 16 hours post infection, the expression was still above baseline levels at 48 hours post infection." (PMID 24204260, 2013). "chabaudi AS-iRBCs (Pc-iRBCs) was observed by intravital microscopy along with an over expression of ICAM-1 on day 7 of the infection, as measured by qRT-PCR." (PMID 24312297, 2013). "LFA-1 is upregulated on infection of primary B-cells by EBV along with ICAM1, LFA-3 and a number of B-cell activation molecules, mimicking the B-cell activation phenotype observed on exposure to antigen or mitogens." (PMID 24068937, 2013). "Tulobuterol (0.1 μmol/L, 72 h) reduced the baseline ICAM-1 mRNA expression in the cells by approximately 35% compared with that of the cells treated with the tulobuterol vehicle (0.001% ethanol) before RV14 infection." (PMID 24303127, 2013).
infection (continued). "Therapies targeting integrins other than MAC1, including humanized anti-CD11a, anti-ICAM1 and anti-CD18, have been associated with increased incidence of infection in clinical trials, including increased fungal and bacterial infections." (PMID 24205223, 2013). "On the contrary, the main driving force behind formation of mDC-CD4+ T-cell conjugates and HIV-1 trans-infection of CD4+ T cells was the interaction between ICAM-1 and LFA-1." (PMID 23590845, 2013). "The level of soluble ICAM-1 (sICAM-1), detected in circulation following proteolytic cleavage of the membrane form, is also believed to increase during infection." (PMID 24386348, 2013). "In ECM, ICAM-1 expression on brain endothelial cells was reported to increase on day 6 post infection, coinciding with a significant increase in microvascular permeability." (PMID 23133375, 2012). "The very low level of ICAM-1 expression in highly differentiated ciliated epithelial cells, as compared to undifferentiated basal cells, appears to limit infection." (PMID 23227049, 2012). "Analysis of mRNA expression of ICAM-1 showed a progressive increase in the response to the presence of the parasite, which reached significant values on 6 and 7 after infection." (PMID 22952850, 2012). "It has been previously reported that ICAM-1/LFA-1 interactions increase the kinetics of infection of the Jurkat-derived cells." (PMID 22970312, 2012). "While our data are in agreement with the reported role of ICAM-1 in HIV-1 binding/infection, the differences between ICAM+ and ICAM− viruses were more modest that those observed previously." (PMID 22970312, 2012). "Significant but variable binding of P. knowlesi infected erythrocytes from human infections to the inducible endothelial receptors ICAM-1 and VCAM was demonstrated here." (PMID 22305466, 2012). "In this work we found an increase of ICAM-1 expression on renal tissue from P. berghei infected mice at day 7 post infection." (PMID 22952850, 2012). "Increased expression of VCAM-1 and ICAM-1 was observed from 24 h post-infection, but the most prominent changes were observed at day 7 after infection." (PMID 22738332, 2012). "Vice versa, in the same cells, ICAM-1 expression was also increased after infection with HRV14 or HRV2." (PMID 23227049, 2012). "Incorporation of intercellular adhesion molecule 1 (ICAM-1) into HIV-1 particles is known to markedly enhance the virus binding and infection of cells expressing lymphocyte function-associated antigen-1 (LFA-1)." (PMID 22970312, 2012). "This is surprising since ICAM-1 has no known clathrin-coated pit localization signals in its cytoplasmic tail and GPI-linked ICAM-1 can mediate HRV14 internalization and infection." (PMID 23227049, 2012). "Another type of macrolide antibiotics, bafilomycin A1 also inhibits infection of RV, in human airway epithelial cells by the reduction of ICAM-1 and by affecting the acidification of endosomes, where RV RNA enters into the cytoplasm of infected cells." (PMID 22719178, 2012). "E-selectin and VCAM-1 expressions increased by ∼100% due to infection, and ICAM-1 expression showed a moderate increase." (PMID 21249123, 2011). "Since expression of ICAM-1 is restricted to the apical surface of polarized epithelial cells in vivo, these results questioned the physiologic significance of transfer infection." (PMID 21573183, 2011). "Mice that received inhaled nitric oxide starting prior to infection had reduced parasitized erythrocyte accumulation in the brain, decreased brain expression of ICAM-1, and preserved vascular integrity compared to control mice." (PMID 22110737, 2011). "In de novo infection and lytic replication, KSHV escapes cytotoxic T cells and NK cells through downregulation of MHC class-I and ICAM-1 molecules and associated antigens involved in forming and sustaining the immunological synapse." (PMID 21509779, 2011).